TNF (tumor necrosis factor)
Diseases named in the same sentence as TNF in open-access papers (continued):
Sharing a sentence is not in itself a finding about the gene and the disease.
Insulin resistance (continued). "In addition, interleukin (IL)-6, IL-8, monocyte chemotactic protein (MCP)-1, and tumor necrosis factor (TNF-α) have also been found to be increased with elevated insulin resistance along with factors such as serum amyloid A, resistin, leptin, and adiponectin." (PMID 23091306, 2012). "MS: Metabolic syndrome; CRP: C-reactive protein; TG: Triglycerides; HDL-C: High-density lipoprotein cholesterol; TC: Total cholesterol; LDL-C: Low-density lipoprotein cholesterol; HOMA-IR: Homeostatic model assessment insulin resistance.; TNF-alpha: Tumor necrosis factor alpha; BMI: Body mass index." (PMID 22691465, 2012). "They interfere with adipocyte function through the production of pro-inflammatory cytokines such as TNF-α, IL-1β and IL-6, which can lead to insulin resistance, modify adipokine secretion and lead to an excess of free fatty acid secretion through increased lipolysis and diminished lipogenesis." (PMID 23201837, 2012). "TNF-α has a well-defined role in the development of insulin resistance in both mice and humans." (PMID 22518292, 2012). "In this experiment we have demonstrated the correlation of expression of TNF-α in RWAT and insulin-resistance in genetically obese fa/fa rats, and that the improvement of NIDDM in these animals by treatment with CL 316,243 is linked with the suppression of TNF-α mRNA expression in WAT." (PMID 23056223, 2012). "Therefore, FTox-G50-induced insulin resistance in skeletal muscle appeared to be TNF-α-independent, and is presumably mediated by other factors." (PMID 22816003, 2012). "Therefore, TNF-α regulation during pregnancy can prevent the deleterious effects of insulin resistance." (PMID 22462002, 2012). "For example, adipose tissue insulin resistance in rats fed with a glutamine-supplemented diet is accompanied by reduced TNFα and interleukin-6 levels, as well as augmented adiponectin levels, which seem to be the cause of increased insulin sensitivity in other organs." (PMID 23024762, 2012). "The association with insulin resistance was partly independent of body fat, but was not related to proinflammatory cytokines TNF-a, IL-6, or MCP-1." (PMID 22984471, 2012). "Since TNF-alpha is a marker of low-grade inflammation, which is present in the insulin-resistant state, it could be also seen as a marker of insulin-resistance, as it is for apelin." (PMID 23227256, 2012). "Because TNF-α is involved in the metabolic regulation of glucose, lipids, and insulin resistance, these data are consistent with the hypothesis that TNF-α is involved in GDM development." (PMID 22462002, 2012). "We examined whether anti-TNF therapy improves insulin resistance in RA patients and assessed changes in the insulin signaling cascade." (PMID 22691241, 2012). "In addition, repeated measures ANOVA revealed a significant effect of anti-TNF treatment (F test = 11.89, P = 0.001) and of the interaction of anti-TNF treatment with baseline insulin resistance group (F test = 24.68, P < 0.001) on HOMA-IR." (PMID 22691241, 2012). "For example, TNFα is known to induce insulin resistance by enhancing secretion of stress hormones." (PMID 22494810, 2012). "IL-1 and TNF-α are involved in obesity-related insulin resistance." (PMID 22272381, 2012). "In summary, we found that 12 weeks of treatment with anti-TNF agents may improve insulin resistance in patients with active RA and high insulin resistance." (PMID 22691241, 2012). "Thus, anti-TNF-α treatment ablates insulin resistance, thereby normalizing the response of host tissues to insulin." (PMID 22606220, 2012). "Inflammatory cytokines such as TNF-α and IL-6 are known to promote insulin resistance." (PMID 21826136, 2012). "Furthermore, the degree of insulin resistance, glucose intolerance, liver steatosis, and adipose and liver inflammatory marker expression (TNFα, IL-6, IL-10, IFN-γ, MCP-1, MIP1α) induced by high fat feeding in CD1d−/− were not different from WT." (PMID 21674035, 2011).
Insulin resistance (continued). "The relationship between central obesity and insulin resistance could be explained based on the metabolism of free fatty acids or other adipocytokines (TNF-α, IL-6, adiponectin) released from the visceral fat." (PMID 22025967, 2011). "We also observed that in the presence of Wortmannin, a biochemical inhibitor of phosphatidylinositol 3-kinase (a hallmark of insulin resistance), VCAM-1 expression was greater in the presence of TNFα plus insulin as compared to that seen with insulin or TNFα alone." (PMID 22093181, 2011). "Adipose tissue secrete IL-6 and TNF-α during insulin resistance, and high levels of TNF-α and IL-6 may downregulate the expression of adiponectin." (PMID 22144985, 2011). "Moreover, pro-inflammatory adipokines, such as tumor necrosis factor- α (TNF-α) and IL-6 lead to the development of insulin resistance." (PMID 21569357, 2011). "Insulin resistance induces high expression of IL-6 and TNF-α mRNA in epididymal adipose tissue." (PMID 22144985, 2011). "All these clinical and experimental observations suggest that TNF-α and IL-6 may be involved in the pathogenesis of insulin resistance, and there is a positive correlation between insulin resistance and inflammation in GDM and macrosomia." (PMID 22144985, 2011). "The insulin resistance-inducing effect of TNF-α is established." (PMID 21556177, 2011). "Other investigators have posited that insulin resistance and hyperinsulinemia may contribute to the increased expression of TNFα, whereby pro-inflammatory mechanisms are increased in the presence of insulin resistance." (PMID 22093181, 2011). "The production of excess TNF-α in tissue was due to insulin resistance." (PMID 21716679, 2011). "molecules involved in the pathogenesis of insulin resistance, such as TNF-α and resistin." (PMID 20652043, 2010). "TNF-α has also systemic effects that result in insulin resistance and type 2 diabetes (T2D)." (PMID 21994721, 2010). "OSA is also characterized by a proinflammatory state and elevated cytokine levels (e.g., tumor necrosis factor-alpha) which may lead to insulin resistance." (PMID 20224753, 2010). "TNF-α is usually elevated in individuals with obesity-induced insulin resistance." (PMID 20224753, 2010). "Adipose tissue has garnered a great deal of attention as a potential source of elevated circulating inflammatory cytokines in obesity and insulin resistance due to many studies demonstrating that adipose tissue can synthesize and secrete pro-inflammatory cytokines, including TNF-α and IL-6." (PMID 21054880, 2010). "High circulating levels of TNF-α, IL-6, and leptin are recognized as markers of insulin resistance." (PMID 21403905, 2010). "Furthermore, TNF α is over expressed in adipose tissue and induces insulin resistance through acute and chronic effects on insulin-sensitive tissues." (PMID 20396393, 2010). "We have examined whether saturated nonesterified fatty acids (NEFA) and insulin, which increase in concentration with developing insulin resistance, can trigger the production of interleukin (IL)-6 and tumor necrosis factor (TNF)-α in human monocytes." (PMID 21054880, 2010). "Taken together, changes in adipocyte gene expression induced by TNF-α could lead to insulin resistance, and NF-κB seems to be an obligatory mediator of most of these TNF-α responses." (PMID 20414465, 2010). "In contrast to the morbidly obese patients, in addition, the elevated TNF-α levels in our septic patients might play a role in insulin resistance." (PMID 20825686, 2010). "In addition, cyanidin-3-glucoside also demonstrates a protective action against H2O2- or TNF-α-induced insulin resistance in 3T3-L1 adipocytes by inhibiting the c-Jun NH2-terminal kinase (JNK) signal pathway." (PMID 20957102, 2010). "Also, inflammatory cytokines including tumor necrosis factor and interleukin 6 are proposed in pathogenesis of hepatocellular injury in insulin resistance/MetS." (PMID 21047423, 2010).
Insulin resistance (continued). "It has been suggested that insulin resistance, through both the activation of nuclear factor kappa B by increased levels of cytokines (i.e., IL-6 and TNF-alpha) and the releasing of free fatty acids by excess adipose tissue, is involved in the pathogenic mechanisms leading to SAHS in humans." (PMID 19262746, 2009). "This discrepancy could be explained by indirect effects of TNFα on insulin resistance, potentially requiring the induction of an additional TNFα dependent mediator of insulin resistance such as cortisol." (PMID 19087258, 2008). "TNFα, and resistin have minor relevance as predictors of stress dependent insulin resistance." (PMID 19087258, 2008). "As such, common variant (s) in the TNF-α, JNK, or NF-kappa B might predict a powerful inflammatory reaction in response to high salt and might possibly explain insulin resistance in Dahl S rats." (PMID 18570670, 2008). "The TNF-α gene locus seems to be involved in human insulin resistance-mediated hypertension." (PMID 18416854, 2008). "However, adiponectin secretion is known to be influenced by factors that induce insulin resistance, which include tumor necrosis factor (TNF)-α, interleukin (IL)-6, C-reactive protein (CRP), lipid metabolism, diet and exercise habits." (PMID 18507868, 2008). "Studies have reported increases in serum TNF-α levels in humans with insulin resistance." (PMID 18782455, 2008). "TNFα has pleiotropic effects on adipocyte physiology including an induction of lipolysis to increase the mobilization of free fatty acids, activating cytokine expression and promoting insulin resistance." (PMID 18549505, 2008). "Since this proteolytic system is involved in the control of receptor-associated (tyrosine-kinase activity insulin receptor), it is postulated here that the mechanism of TNF-α-induced insulin-resistance is mediated by the activation of the UPS-dependent proteolysis." (PMID 17971205, 2007). "TNF-alpha-induced insulin resistance has received much recent attention." (PMID 17140429, 2006). "According to a unifying hypothesis, HSV-1, CMV, H. pylori and Chlamydia pneumoniae induce production of proinflammatory cytokines, such as TNF-alpha and IL-6 which are leading to chronic subclinical inflammation, insulin resistance and the metabolic syndrome." (PMID 17140429, 2006). "Tumor necrosis factor-α (TNFα) is a mediator of insulin resistance." (PMID 16803616, 2006). "Insulin resistance and another inflammatory state, atherosclerosis, share similar pathophysiological mechanisms, mainly due to the actions of the two major proinflammatory cytokines, TNF-alpha and IL-6." (PMID 17140429, 2006). "Our data do not support a role for TNF alpha, ghrelin, leptin or adiponectin in the insulin resistance associated with short-term glucocorticoid treatment." (PMID 16965635, 2006). "One of the main metabolic effects of TNFα action is the development of insulin resistance." (PMID 16803616, 2006). "Interestingly, the peak in TNFα and IL-6 levels after LPS administration to humans precedes a phase of prolonged insulin resistance that begins approximately 6 h after LPS administration, closely approximating the time course of resistin induction." (PMID 15578112, 2004). "Furthermore, a diet high in fatty acids, has been suggested to induce hepatic insulin resistance, resulting in increases in plasma TNF-α and IL-6, in apo-CIII-overexpressing mice, with an increase in apo-CIII playing a major role in liver inflammation and cell death in patients with MASLD." (PMID 39941760, 2025). "Individuals with metabolic features such as central adiposity or insulin resistance may be evaluated using IL-6/TNF panel testing, whereas those with autoimmune features, such as photosensitivity, anti-dsDNA positivity, or low complement, may be tested using an ISG/Type I interferon panel." (PMID 41440484, 2025).
Insulin resistance (continued). "In insulin resistance states, microglial cell function is disrupted, causing polarization toward the pro-inflammatory M1 phenotype and the release of inflammatory factors such as TNF-α (Tumor Necrosis Factor-alpha) and IL-1β (Interleukin-1 beta), which result in cellular damage." (PMID 40895109, 2025). "Furthermore, it has been observed that individuals with diabetes exhibit increased levels of pro-inflammatory cytokines, such as interleukin-6 (IL-6) and tumor necrosis factor-α (TNF-α), which contribute to chronic inflammation, exacerbating pancreatic β-cell damage and insulin resistance." (PMID 40917351, 2025). "TNF-alpha is involved in systemic inflammation and the acute phase reaction, control of immune cells, fever, apoptotic cell death, and sepsis; autoimmune diseases, insulin resistance, and cancer are some conditions in which the levels of TNF-alpha are increased." (PMID 40327662, 2025). "In addition, visceral fat accumulation was related to insulin resistance, glucose intolerance, elevated levels of C-reactive protein and tumor necrosis factor-α, all of which may further exacerbate CVDs." (PMID 40699163, 2025). "Interestingly, those expressions of “contractil genes” are associated to an increase of pro-inflammatory cytokines (TNFα, IL6 or IL1b) in insulin-resistance condition, while the presence of minoxidil or nebivolol reduces significantly the expressions of IL6 and IL1b." (PMID 41049496, 2025). "Insulin resistance may contribute significantly to the development of MASLD and its induced abnormalities in lipid metabolism can lead to increased production of proinflammatory cytokines, such as TNF-α, IL-1b, and IL-6, as well as less adiponectin, thereby inducing systemic insulin resistance." (PMID 40567989, 2025). "First, insulin resistance promotes neuroinflammation, characterized by chronic low‐grade inflammatory responses, elevating pro‐inflammatory cytokines (such as interleukin‐6 [IL‐6] and tumor necrosis factor alpha [TNF‐α]), which impair neuroplasticity and enhance neuronal vulnerability." (PMID 41024619, 2025). "As the primary mediators, the inflammatory factors TNF-α and IL-6 cooperated with other factors to inhibit or damage insulin secretion by pancreatic islet beta cells and simultaneously reduce the activity of insulin receptors, thus leading to insulin resistance." (PMID 40842498, 2025). "Mechanistically, AβOs may induce or exacerbate neuronal insulin resistance through the aberrant activation of the TNF-α/JNK (tumor necrosis factor α/c-Jun N-terminal kinase) pathway, leading to serine phosphorylation of IRS-1 and inducing mitochondrial oxidative stress." (PMID 39966707, 2025). "Our analysis identified the TNF signaling pathway (p = 1.08 × 10−6), insulin resistance (p = 4.91 × 10−5), and Hippo signaling pathway (p = 9.80 × 10−5) as the most significantly enriched pathways, exhibiting notable impact values (e.g., 0.68 for insulin resistance)." (PMID 40806239, 2025). "Excess adiposity contributes to insulin resistance through increased free fatty acid flux, ectopic fat deposition, and chronic low-grade inflammation driven by adipokines and pro-inflammatory cytokines such as tumour necrosis factor-alpha (TNF-α) and interleukin-6 (IL-6)." (PMID 41395632, 2025). "Previous studies suggest that pro-inflammatory cytokines (e.g., TNF) induce inflammatory signaling and insulin resistance, suggesting that allosteric activation may be a potential marker of inflammatory signaling and insulin resistance." (PMID 40943574, 2025). "Fecal microbiota transplantation is a safe therapeutic method that can inhibit weight gain in BTBRob/ob mice, reduce proteinuria, decrease the local expression of tumor necrosis factor-α (TNF-α) in the ileum and ascending colon, and may improve insulin resistance." (PMID 40735439, 2025). "Similarly, TNF-α exacerbates insulin resistance by impairing insulin receptor signaling." (PMID 40218134, 2025).
Insulin resistance (continued). "Insulin resistance has been mainly related to high-fat and high-carbohydrate diets leading to fat mass gain in overweight and hence often related to obesity, particularly visceral fat accumulation, which leads to the release of pro-inflammatory cytokines like TNF-α, IL-6, and resistin." (PMID 40136728, 2025). "Consequently, TNF-α concentrations throughout pregnancy may contribute to the physiological insulin resistance that permits glucose availability to the developing fetus." (PMID 39519203, 2024). "Furthermore, adipose tissue macrophages, which are recruited to adipose tissue in obesity, also play a critical role in promoting inflammation and insulin resistance through the secretion of pro-inflammatory cytokines and adipokines such as TNF-alpha and interleukin-1 beta." (PMID 39617908, 2024). "The promoting mechanism of TSH on insulin resistance may be due to its ability to induce the expression of a variety of inflammatory factors including interleukin-6 and tumor necrosis factor-α in adipocytes, and the inflammatory response can enhance islet resistance." (PMID 39525852, 2024). "In addition, some meta-analyses of randomized controlled trials revealed that selenium supplementation significantly increased systolic blood pressure, tumor necrosis factor-alpha (an inflammatory trigger for insulin resistance), and low-density lipoprotein cholesterol." (PMID 39882034, 2024). "Therefore, tapering the macrophage TNFα release may be responsible for the improvements seen in the course of several diseases (e.g., atherosclerosis, steatohepatitis, insulin resistance)." (PMID 39452935, 2024). "Similarly, a 5-week dietary intervention with mung bean peptide (245 mg/kg/day) in high-fat-diet-treated mice demonstrated notable improvements in insulin resistance, body weight, and several serum biomarkers including fasting blood glucose, C-peptide, IL-6, TNF-α, and MDA." (PMID 39203819, 2024). "Furthermore, insulin resistance can augment the levels of inflammatory mediators, such as tumor necrosis factor-α (TNF-α) and interleukin-6 (IL-6), which may exacerbate inflammatory processes within cardiac tissues and impair heart function." (PMID 38956581, 2024). "In obese individuals, an increase in circulating TNF-α due to an overall increase in fat tissue could lead to breast cancer tumorigenesis by contributing to insulin resistance and IL-6 synthesis regulation, considering that TNF-α was identified as a key regulator of IL-6 synthesis." (PMID 38247865, 2024). "Phytol plays a promising role in the management of insulin resistance by modulating the transcription activity of peroxisome proliferator-activated receptor alpha and retinoid X receptor, increasing the serum adiponectin level and decreasing the level of TNF-α." (PMID 39479139, 2024). "Also, activation of JNK seems to be involved in TNFα-induced insulin resistance." (PMID 38953241, 2024). "Moreover, the focus on TNF-α may overlook the chronic nature of insulin resistance observed in vivo." (PMID 39627194, 2024). "Proinflammatory cytokines, such as tumor necrosis factor (TNF-α), interleukin-6 (IL-6), and nuclear factor B (NF-B), have been implicated in the activation of various intracellular inflammatory signaling pathways, including JNK and IKK, which can lead to glucose and insulin resistance." (PMID 38048013, 2024). "Importantly, the TNF-α-treated adipospheres (WA-TNF-α) distinctly exhibited insulin resistance." (PMID 38820505, 2024). "Additionally, insulin resistance increases the M1 proinflammatory response of macrophages, even increasing the secretion of TNF-α and other cytokines that can worsen vascular function, and decreases the M2 anti-inflammatory response by reducing the synthesis of IL-10." (PMID 38542702, 2024). "Additionally, TNF-α contributes to insulin resistance, leading to hyperglycaemia." (PMID 38473761, 2024).